COL6A3 (collagen type VI alpha 3 chain)
Diseases named in the same sentence as COL6A3 in open-access papers (continued):
Sharing a sentence is not in itself a finding about the gene and the disease.
rectal adenocarcinoma (2 papers, 2015 to 2020). "COL6A3 mRNA was found to be significantly upregulated in rectal adenocarcinoma tissues comparing with normal rectum tissues (p = 8.4E-16), as revealed by analyzing Gaedcke Colorectal dataset." (PMID 26338966, 2015).
schizophrenia (2 papers, 2019 to 2025). A major psychotic disorder characterized by abnormalities in the perception or expression of reality. "However, HAL action dysregulated other genes also associated with schizophrenia in humans, such as Col6a3, Slc22a8, and Bmal1." (PMID 39825014, 2025). "HAL and KARI201 antipsychotic effects were associated with targeting expression of other schizophrenia associated genes like Col6a3, Slc22a8, and Bmal1, or Nr2f6a, respectively, but none affecting expression of sphingolipid regulating genes." (PMID 39825014, 2025).
tenosynovial giant cell tumor (2 papers, 2019 to 2025). A tumor usually arising in the synovium of joints, bursa or tendon sheath. "On the other hand, patients with malignant tenosynovial giant cell tumors, defined by COL6A3::CSF1 fusion and low percentage neoplastic cells, are better diagnosed by target PCR instead of OGM." (PMID 40141463, 2025).
adenoma (1 paper, 2024). A neoplasm arising from the epithelium. "Other frequently enriched genes in adenoma include collagen family members such as COL6A1, COL6A2, and COL6A3." (PMID 39408697, 2024).
ampullary carcinoma (1 paper, 2023). "The m/z values (peptides) from PLEC, AHNAK and COL6A3 proteins show significantly higher intensity-distributions in the tumor region of ductal adenocarcinoma, in comparison with ampullary carcinoma." (PMID 36765644, 2023).
atopic dermatitis (1 paper, 2024). "Surprisingly, neither COL6A3, PPCS, nor IL6R levels were causally associated with increased risk of coronary atherosclerosis in this cohort, although higher levels of circulating IL6 receptor were causally associated with increased risk of atopic dermatitis." (PMID 38989470, 2024).
bladder tumor (1 paper, 2022). "We compared the mRNA expression of CDH11, COL6A3, EDNRA, and SERPINF1 between bladder tumor and neighboring healthy tissues, respectively." (PMID 36595851, 2022).
bronchopulmonary dysplasia (1 paper, 2024). Bronchopulmonary dysplasia is a chronic respiratory disease that results from complications related to lung injury during the treatment of infant acute respiratory distress syndrome in low-birth-weight premature infants or from abnormal lung development in older infants. "The first had a heterozygous variant (rs148175795) in COL6A3, which suggested a bronchopulmonary dysplasia phenotype." (PMID 37482595, 2024). "The first infant was heterozygous for a variant (rs148175795) in COL6A3, which suggested a bronchopulmonary dysplasia phenotype." (PMID 37482595, 2024).
cervical dystonia (1 paper, 2023). "We identified a novel deleterious compound heterozygous mutation as well as five missense variants in the COL6A3 gene of Chinese patients with cervical dystonia." (PMID 37082441, 2023). "Among 45 isolated cervical dystonia patients, 18 patients (10 female patients and eight male patients) were found to have seven potential causal variants in the COL6A3 gene." (PMID 37082441, 2023). "Here, we examined genetic information on the COL6A3 gene in 45 Chinese patients with isolated cervical dystonia and found that 18 patients had seven potential causal variants in the COL6A3 gene." (PMID 37082441, 2023). "In conclusion, we identified a novel deleterious compound heterozygous mutation in the COL6A3 gene in Chinese patients with cervical dystonia." (PMID 37082441, 2023). "After analyzing the genetic information of 45 Chinese patients with isolated cervical dystonia by whole-exome sequencing, we found that 18 (10 female patients and eight male patients) patients had variants of COL6A3 (NM_004369.4, OMIM 120250)." (PMID 37082441, 2023). "Therefore, in this study, we analyzed the mutations of COL6A3 in 45 Chinese patients with isolated cervical dystonia by next-generation sequencing and tried to identify potential causal variants of COL6A3." (PMID 37082441, 2023).
chronic kidney disease (1 paper, 2025). Impairment of the renal function secondary to chronic kidney damage persisting for three or more months. "The biomarker of COL6 formation, PRO-C6, can also quantify the profibrotic and proinflammatory COL6A3-derived molecule endotrophin, which has been shown to be a common biomarker of the risk of chronic kidney disease (CKD) and CVD." (PMID 40142664, 2025).
colorectal tumors (1 paper, 2016). "These eight isoforms encoded by OGDH, COL6A3, ICAM1, PHPT1, PPP2R5D, SLC29A1, and TRIB3 genes were up-regulated in colorectal tumors, and this is in concordance with the bioinformatics data." (PMID 28105922, 2016).
corneal diseases (1 paper, 2020). "Given the emerging evidence of ER stress in relation with several corneal diseases, we next examined whether cells containing the retained mutant COL6A3 protein presented features of ER stress." (PMID 33304895, 2020).
Corneal opacity (1 paper, 2020). A reduction of corneal clarity. "The patient carrying COL6A3 mutations was a Han Chinese boy with bilateral corneal opacity, born to healthy parents after an uneventful pregnancy." (PMID 33304895, 2020).
Crohn disease (1 paper, 2025). A gastrointestinal disorder characterized by chronic inflammation involving all layers of the intestinal wall, noncaseating granulomas affecting the intestinal wall and regional lymph nodes, and transmural fibrosis. "Type III and VI collagens are highly associated with intestinal fibrosis, with the alpha-3 chain of type VI collagen (COL6A3) being particularly elevated in intestinal tissues from ulcerative colitis (UC) and Crohn’s disease (CD) patients." (PMID 40142664, 2025).
dermatomyositis (1 paper, 2023). Dermatomyositis (DM) is a type of idiopathic inflammatory myopathy characterized by evocative skin lesions and symmetrical proximal muscle weakness. "The expression of COL6A3 in V727M mutation–harboring GNE patients was higher than 2.5-fold in comparison to all myositis (Polymyositis, Inclusion-Body Myositis, Dermatomyositis, and Non-specific myositis)." (PMID 36980840, 2023).
dilated cardiomyopathy (1 paper, 2023). Cardiomyopathy which is characterized by dilation and contractile dysfunction of the left and right ventricles. "Notably, among these proteins, MYL2, ACTN1, MYLK, COL1A2, COL6A2, and COL6A3 have been associated with dilated cardiomyopathy and hypertrophic cardiomyopathy pathogenic processes in previous studies." (PMID 37649075, 2023).
dyslipidemia (1 paper, 2019). "COL6A3 SNPs were also found to confer susceptibility to early-onset dyslipidemia." (PMID 31286980, 2019).
Floating-Harbor syndrome (1 paper, 2023). Floating-Harbor syndrome is a genetic developmental disorder characterized by facial dysmorphism, short stature with delayed bone age, and expressive language delay. "Three of the coding genes (RCAP, RP11-83N9.5, and COL6a3) were found to be associated with floating harbor syndrome, retinitis pigmentosa, and myopathy disorder, respectively." (PMID 36980840, 2023).
glioma (1 paper, 2025). A benign or malignant brain and spinal cord tumor that arises from glial cells (astrocytes, oligodendrocytes, ependymal cells). "We next performed survival analysis on the top 30 signature genes of COL6A3+ TAFs via the Cancer Genome Atlas (TCGA)-GBM/LGG RNA sequencing (RNA-seq) dataset and the Chinese Glioma Genome Atlas (CGGA)-GBM/LGG RNA-seq dataset." (PMID 41174767, 2025). "The results showed that COL6A3 is highly expressed in GBM, while its expression is much lower in lower-grade gliomas and normal brain tissue." (PMID 41174767, 2025).
gliosarcoma (1 paper, 2019). A rare histological variant of glioblastoma (WHO grade IV) characterized by a biphasic tissue pattern with alternating areas displaying glial and mesenchymal differentiation (WHO). "COL6A3 appears to be a good marker of gliosarcoma tumors, as its expression was very high in the sarcomatous component, while it was virtually absent in the gliomatous component." (PMID 30818875, 2019). "When compared to GBMs, gliosarcomas show up-regulation of some genes, ranging up to a 6-fold difference on a log2-scale and most top differentiating genes encode collagens (COL1A1, COL6A1, COL6A2, COL6A3, COL1A2, COL3A1)." (PMID 30818875, 2019).
GNE myopathy (1 paper, 2023). "To further explore the role of the COL6a3 gene in inducing GNE myopathy, we investigated the COL6a3 coexpressing gene sets." (PMID 36980840, 2023). "Further, we looked for deregulation of Col6A3 in GNE myopathy in comparison to the different myositis data." (PMID 36980840, 2023).
human papillomavirus infection (1 paper, 2021). "KEGG signaling pathway analysis showed that circRNAs are enriched in PI3K/AKT, human papillomavirus infection (HPI), focal adhesion (FA), and other seven pathways, and VWF and COL6A3 were involved in 4/7 pathways." (PMID 34527744, 2021).
hypospadias (1 paper, 2025). Hypospadias is the displacement of the urethral meatus on the ventrum of the penis. "Notably, COL6A3 expression has been reported to be upregulated in DNAH17 mutants associated with severe hypospadias, suggesting a possible link that merits closer examination." (PMID 41300791, 2025). "However, COL6A3 gene expression was upregulated in DNAH17 mutants detected in severe hypospadias and therefore requires further assessment." (PMID 41300791, 2025). "Additionally, we detected variants of uncertain significance in hypospadias-related gene families (DNAH12 and LHFP) and in other genes, such as COL6A3, which may cause the phenotype." (PMID 41300791, 2025).
keratoconus (1 paper, 2023). A degenerative, structural disorder of the eye, characterized by a cone-shaped protrusion of the cornea. "Mutations in COL6A3 appear in keratoconus patients, which seems to point to it as a possible candidate gene." (PMID 37895187, 2023).
kidney cancer (1 paper, 2016). Primary or metastatic malignant neoplasm involving the kidney. "Using qPCR method, we showed the tumor-specific overexpression of uc002vwo/NM_057167 COL6A3 alternative transcript in colorectal, breast, lung, prostate, and kidney cancers." (PMID 28105922, 2016).
laryngeal carcinoma (1 paper, 2020). Carcinoma that arises from the laryngeal epithelium. "In our RNA-seq results, COL6A1, COL6A2, and COL6A3 were downregulated at mRNA levels in MYCT1 overexpressing laryngeal cancer cells (GSE123275)." (PMID 33680912, 2020). "We also found that both COL6A2 and COL6A3 knockdown significantly recued the effects of MYCT1 silence on their expressions in laryngeal cancer cells (P < 0.01), respectively." (PMID 33680912, 2020). "This implies that COL6A1, COL6A2, and COL6A3 are crucial in laryngeal cancer." (PMID 33680912, 2020). "At the mRNA level, Knockdown of MYCT1 significantly increased the COL6A1, COL6A2, and COL6A3 expression but MYCT1 decreased the COL6A2, and COL6A3 expression in laryngeal cancer cells (P < 0.01), respectively." (PMID 33680912, 2020). "In MYCT1-overexpressing laryngeal cancer cells, another 13 DEGs (GSE123275) were overlapped in the GSE6631 and TCGA datasets, where COL6A1, COL6A2, and COL6A3 were also present." (PMID 33680912, 2020). "COL6A2 and COL6A3 knockdown significantly recued the effects of MYCT1 silence on the adhesion, migration and wound healing abilities of the laryngeal cancer cells (P < 0.01), respectively." (PMID 33680912, 2020).
leiomyoma (1 paper, 2013). A well-circumscribed benign smooth muscle neoplasm characterized by the presence of spindle cells with cigar-shaped nuclei, interlacing fascicles, and a whorled pattern. "The genes associated with “cancer process” contained potentially novel or relevant candidate genes for leiomyoma formation such as IRS1, COL4A1, COL4A2, COL6A3, and GSTM5." (PMID 23818951, 2013). "IRS1 is also reported to be involved in the upregulation of collagen genes, including COL4A1, COL4A2 and COL6A3, suggesting that IRS1 possibly contributes to the leiomyoma nodule formation by upregulating the gene expression of COL4A1, COL4A2, and COL6A3." (PMID 23818951, 2013).
Lipedema (1 paper, 2022). Disorder of adipose tissue characterized by symmetric and bilateral enlargement of the lower extremities due to abnormal deposition of subcutaneous fat often in obese women. "Immunohistochemistry results have confirmed that differentiated spheroids derived from lipedema ADSCs showed higher expression levels of basement membrane components of laminin (LAM) and collagen VI (COL6A3) and lower expression of fibronectin (FN) compared to undifferentiated and healthy spheroids." (PMID 36551837, 2022). "Furthermore, the slight decrease in MMP11 expression in lipedema may contribute to excess collagen deposition, as MMP11 is known to cleave COL6A3, eventually reducing collagen deposition." (PMID 36551837, 2022).
liver cancer (1 paper, 2020). An epithelial or non-epithelial malignant neoplasm that arises from the liver. "Here, we studied the effects of the Col6a3-derived peptide ETP on the progression of chronic liver diseases, such as NASH and liver cancer." (PMID 33110211, 2020).
lymphoma (1 paper, 2023). A malignant (clonal) proliferation of B- lymphocytes or T- lymphocytes which involves the lymph nodes, bone marrow and/or extranodal sites. "Among the novel N3a-sensitive PI3K/mTOR-reducing proteins in lymphomas, were increased PHLDA3 (R_cHL/MCL), OSMR (R_cHL), COL6A3, and Rictor (P_ALCL/cHL)." (PMID 37568720, 2023).
Myocardial fibrosis (1 paper, 2024). "COL6A3 is known to promote the formation of collagen fibers, consequently inducing myocardial fibrosis and expediting atrial remodeling." (PMID 38368363, 2024).
neuroendocrine tumors (1 paper, 2020). "Among these, known biomarkers for MB (FSTL5), and other tumor types such as neuroendocrine tumors (ENO2, FMOD, ART3, COL6A3) and PIP, were found to be significantly up-regulated (dark green)." (PMID 32466393, 2020).
non-alcoholic fatty liver diseases (1 paper, 2020). "Intriguingly, our previous studies showed that EGCG treatment shared four common collagen-related genes Col1a1, Col1a2, Col3a1 and Col6a3 with atorvastatin treatment in non-alcoholic fatty liver diseases." (PMID 32290071, 2020).
ovarian clear cell cancer (1 paper, 2024). An invasive malignant neoplasm that arises from the ovary and is characterized by a predominance of clear and hobnail malignant epithelial cells. "The combination of everolimus (a mTOR inhibitor) and 5-aza-2-deoxycytidine (a demethylating agent) can effectively inhibit the production of ovarian clear-cell cancer stem-like or spheroid cells by inhibiting the COL6A3-AKT-mTOR pathway and exerting an anti-tumor effect." (PMID 39125689, 2024).
pituitary adenomas (1 paper, 2025). "The overexpression of the COL6A3 gene in pituitary adenomas has been correlated with the suppression of tumor growth and metastasis capacity." (PMID 40328795, 2025).
preeclampsia (1 paper, 2025). Preeclampsia is a hypertensive disorder of pregnancy that is characterized by new-onset hypertension with proteinuria presenting after 20 weeks of gestation, and depending on mild or severe forms may initially present with severe headache, visual disturbances, and hyperreflexia. "The upregulation of COL6A3, encoding the α3 chain of collagen VI, is particularly noteworthy as it was specifically observed in preeclampsia males compared to control males, despite previous studies finding no dysregulation in preeclampsia." (PMID 41444673, 2025).
Sepsis (1 paper, 2020). Sepsis is defined as life-threatening organ dysfunction caused by a dysregulated host response to infection. "The profile of MYL9 associated gene interactions for adult sepsis is quite different than that for pediatric sepsis, with association instead with platelet membrane glycoproteins GP5 and GP6, PLOD2, COL6A3, and PROS1." (PMID 32318053, 2020).
serous ovarian carcinoma (1 paper, 2024). "COL6A3 showed strong staining in cancerous stromal cells but not in cancer cells of high-grade serous ovarian carcinoma paraffin-embedded tissue (as determined via immunohistochemistry)." (PMID 39125689, 2024).
sickle cell disease (1 paper, 2022). Sickle cell anemias are chronic hemolytic diseases that may induce three types of acute accidents: severe anemia, severe bacterial infections, and ischemic vasoocclusive accidents (VOA) caused by sickle-shaped red blood cells obstructing small blood vessels and capillaries. "Bantu, Afro-related ethnolinguistic cultural groups, and Latin America have a similar low proportion of pathogenic variants in most of the sickle cell disease-specific genes, except in MY O 7B, CPS1, COL6A3, MTRR, SLC22A5, ABCC1, and RPL3L." (PMID 35812734, 2022).
Sinus bradycardia (1 paper, 2021). Bradycardia related to a mean resting sinus rate of less than 50 beats per minute. "In our population, two heterozygous missense VUSs in COL6A3 gene (c.1214T>C) and FKTN gene (c.-7C>G) were reported in a 61-year-old male with NM with sinus bradycardia, first degree AV block, and right axis deviation in ECG, as well as LVH in TTE." (PMID 33567613, 2021).
soft tissue sarcoma (1 paper, 2025). A malignant neoplasm arising from muscle tissue, adipose tissue, blood vessels, fibrous tissue, or other supportive tissues excluding the bones. "In a different soft tissue sarcoma, undifferentiated pleomorphic sarcoma, COL6A3 is predictive of poor outcomes." (PMID 40507266, 2025). "Further work is ongoing to validate the mechanism and prognostic utility of COL6A3 in soft tissue sarcomas." (PMID 40507266, 2025).
stenosis (1 paper, 2014). "Further, the up-regulation of an isoform of collagen (i.e. COL6A3) in the iTRAQ result may indicate accumulation of extracellular matrix components that could cause collagenosis and vascular stenosis thus aggravating the perfusion failure." (PMID 24448401, 2014).
triple-negative breast carcinoma (1 paper, 2018). An invasive breast carcinoma which is negative for expression of estrogen receptor (ER), progesterone receptor (PR), and human epidermal growth factor receptor 2 (HER2). "COL6A3 represents a frequently mutated gene in triple negative breast cancers." (PMID 29719832, 2018).
Uterine leiomyoma (1 paper, 2013). The presence of a leiomyoma of the uterus. "In the present study, the gene expressions of COL4A1, COL4A2 and COL6A3 were found to be increased in uterine leiomyomas." (PMID 23818951, 2013).